MMP2 (matrix metallopeptidase 2)
Diseases named in the same sentence as MMP2 in open-access papers (continued):
Sharing a sentence is not in itself a finding about the gene and the disease.
osteosarcoma (continued). "MMP-2 and MMP-9 have been demonstrated to be overexpressed in osteosarcoma and promote lung metastasis, and regulation of these enzymes is associated with other metabolic pathways that are overexpressed in osteosarcoma, including de novo serine biosynthesis." (PMID 33809018, 2021). "Studies have shown that MMP-2 and MMP-9 are involved in AKT/mTOR-mediated invasion and metastasis of osteosarcoma cells." (PMID 34953496, 2021). "In a past study of metastatic human osteosarcoma cells, quercetin clearly diminished expression of PTHR1 mRNA, thus attenuating expression levels of MMP‐2 and MMP‐9 mRNA and ultimately reducing cellular invasion, adhesion, proliferation and migration." (PMID 33675132, 2021). "Inhibition of microRNA-328 by resveratrol (3,5,4′-trihydroxystilbene, a natural polyphenol) suppressed MMP-2, and the ability of MNNG/HOS osteosarcoma cells to metastasize after intra-tibial injection in SCID mice." (PMID 32377334, 2020). "Then, in osteosarcoma cells, we evaluated COLGALT2, vimentin and matrix metalloproteinase 2/9 (MMP2/9) expression together with ADSC exosomes using qRT-PCR and western blotting." (PMID 32523950, 2020). "Studies have revealed that MMPs including MMP-1, MMP-2, MMP-3, MMP-7, MMP-9, MMP-12, and MMP-13 are significantly related to osteosarcoma metastasis and poor prognosis." (PMID 33228783, 2020). "In osteosarcoma cells, piperine increased the expression of TIMP1 and -2 that in turn inhibited MMP-2/9, further contrasting metastasization." (PMID 33256185, 2020). "To identify the mediator of TSP‐2‐promoted osteosarcoma migration, we examined levels of MMP‐1, MMP‐2, MMP‐3, MMP‐7, MMP‐9, MMP‐12 and MMP‐13 mRNA expression following TSP‐2 stimulation." (PMID 33021341, 2020). "Studies have revealed that MMPs such as MMP-2, MMP-3, and MMP-9 are involved in osteosarcoma progression and metastasis." (PMID 33228783, 2020). "To identify the mediator of MCP-1-promoted osteosarcoma migration, we further examined the expression of MMP-1, MMP-2, MMP-3, MMP-7, MMP-9, MMP-12, and MMP-13 mRNA under MCP-1 stimulation." (PMID 33228783, 2020). "Briefly, the current study demonstrated the lncARSR increased in ADM-resistant osteosarcoma cells, induced overexpression of MRP1, Survivin, and MMP2 via activating AKT." (PMID 32404870, 2020). "We also previously demonstrated that, by controlling MMP2/MMP9 expression and activity, the JNK/c-Jun signaling pathway plays a key role in osteosarcoma potential for metastasis." (PMID 30642298, 2019). "Specifically, we demonstrate here that WIN markedly reduced the migratory ability of osteosarcoma MG63 cells, and this effect was accompanied by a dramatic reduction in the extracellular activity and intracellular levels of MMP2 and MMP9 metalloproteases." (PMID 31652569, 2019). "The ability of the osteosarcoma cell line Saos-2 to induce new blood vessel formation by upregulation of angiogenic growth factors like VEGF165, FGF2, MMP2 and MMP9 has already been shown." (PMID 30986223, 2019). "Nobiletin inhibits human osteosarcoma U2OS and HOS cells’ motility, migration and invasion by down-regulating MMP-2 and MMP-9 expressions via ERK pathways." (PMID 30960968, 2018). "It was indeed reported that inhibiting this pathway decreases both the MMP2 and the MMP9 activities, further impeding the metastatic spreading of the murine Osteosarcoma cell line LM8, nevertheless highly aggressive." (PMID 30515265, 2018). "Studies have shown that ECM degradation mediated by MMP-2 and MMP-9 plays a critical role in the motility and invasiveness of osteosarcoma cells." (PMID 30235848, 2018). "In various osteosarcoma cells, PC4 knockdown reduced MMP9 and MMP2 mRNA levels, compared to each parental cell respectively (Figure 5A1-5A4)." (PMID 28881805, 2017). "In the current study, knockdown of DRP5 resulted in a remarkable downregulation of MMP‐2 and MMP‐9, which was consistent with the reduced numbers of osteosarcoma cells with migratory and invasive activities." (PMID 28374915, 2017).
osteosarcoma (continued). "Here, we found that the expression of MMP-2 was diminished after the BMPR2-depleted in 143B cells, so we suggest that MMP2 were involved in the BMPR2-induced MET in osteosarcoma cells." (PMID 28938584, 2017). "And MMP-2 and MMP-9, two of the major proteases, which contribute to migration and invasion in osteosarcoma pathogenesis." (PMID 29156780, 2017). "Other studies, however, have shown that colchicine treatment can influence MMP-2 activity and MMP-14 gene expression in osteosarcoma cells." (PMID 30931350, 2017). "We found reduced expressions of MT1-MMP, MMP-2, and MMP-7 after EZH2 knockdown in osteosarcoma cells." (PMID 27223261, 2016). "Further, their data identified miR-519d down-regulation via connective tissue growth factor (CTGF) signaling as a pathway osteosarcoma cells utilize to upregulate MMP-3 and MMP-2 expression." (PMID 27562075, 2016). "HOTAIR is commonly overexpressed in osteosarcoma, and its knockdown significantly inhibits cellular proliferation and invasion by decreasing MMP-2 and MMP-9 section in osteosarcoma cells." (PMID 27685633, 2016). "Nobiletin inhibits osteosarcoma cell metastasis by suppressing the expression and binding activities of NF-κB and CREB on MMP-2 and MMP-9 promoters." (PMID 27144433, 2016). "In osteosarcoma cells, we found that RESV inhibited the migration/invasion in vitro and lung metastasis in vivo by suppressing matrix metalloproteinase (MMP)-2." (PMID 25605016, 2015). "In osteosarcomas, we first showed that RESV can inhibit the MMP-2 protein level of tumor cells in vitro and in vivo." (PMID 25605016, 2015). "In osteosarcoma, sorafenib inhibits the proliferation of tumor, angiogenesis (VEGF), invasion (MMP2), the emergence of pulmonary metastases (Erzin/β4-integrin/ PI3K) and induces apoptosis." (PMID 26541413, 2015). "Expression of CTGF, MMP-2, and MMP-3 in osteosarcoma patients was significantly higher than in normal bone." (PMID 25003330, 2014). "Doxycycline, epigallocatechin gallate, nutrient mixture (NM), actinomycin-D, cyclohex-amide, retinoic acid and dexamethasone inhibited MMP-2 and -9 in U2OS osteosarcoma cells." (PMID 24190483, 2014). "Results indicated CTGF inducing upregulation of MMP-2 and MMP-3 expression in human osteosarcoma cells by down-regulating miR-519d through MEK and ERK pathway and contributing the tumor metastasis." (PMID 25003330, 2014). "This study characterized effect of CTGF on production of MMP-2 and MMP-3 in human osteosarcoma, which is responsible for subsequent increased migration and metastasis." (PMID 25003330, 2014). "MMP-2 and MMP-9 are overexpressed in osteosarcoma and promote osteosarcoma cell migration and invasion by degrading certain components of the basement membrane and epimatrix." (PMID 23946787, 2013). "In thisin vitrostudy, the NM significantly inhibited secretion of u-PA and MMP-2 and/or -9 and increased secretion of TIMP-2 in osteosarcoma and rhabdomyosarcoma cells, suggesting its potential in modulating cancer invasion and metastasis." (PMID 23900236, 2013). "This study suggests that risedronate downregulates the expressions of MMP-2 and MMP-9 in osteosarcoma, and that this is responsible for its effect on osteosarcoma cell invasiveness." (PMID 19624845, 2009). "In the present study, we found that risedronate suppresses cell invasion and the gelatinolytic activities and protein and mRNA expressions of MMP-2 and MMP-9 in the SaOS-2 and U2OS osteosarcoma cell lines." (PMID 19624845, 2009). "Accordingly, our findings demonstrate that risedronate has anti-invasive and antimetastatic activity via the inhibition of MMP-2 and MMP-9 activity in human osteosarcoma cells." (PMID 19624845, 2009).
osteosarcoma (continued). "Studies have shown that in the osteosarcoma cell line U20S, the activation of the NF-κB signaling pathway can up-regulate key metastasis-promoting factors such as vascular endothelial growth factor (VEGF), MMP2 and MMP9." (PMID 40786506, 2025). "Furthermore, the upregulation of matrix metallopeptidase genes, including MMP1, MMP2, MMP9, MMP11, and MMP16, has been observed in osteosarcoma (OS)." (PMID 38966281, 2024). "In the current study, we confirmed that NGF promotes the migration of osteosarcoma cells by mediating the production of MMP-2, rather than other MMPs." (PMID 38816365, 2024). "Valproic acid decreases the expression of MMP2 and MMP9 mRNAs in osteosarcoma cells." (PMID 39253583, 2024). "The rate of pJNK positivity in osteosarcoma cells with high LRP1–SNRNP25 expression was significantly higher than that in the corresponding control cells (80% vs. 40%), and MMP2 expression was also higher in cells with high LRP1–SNRNP25 expression (100% vs. 30%)." (PMID 38678020, 2024). "We investigated the effects of sublethal doxorubicin concentrations on osteosarcoma cells lacking the MMP‐2 gene to identify an additional target for enhancing doxorubicin effectiveness." (PMID 38064181, 2023). "In the current study, we examined the impact of sublethal concentrations of doxorubicin on enhancing the invasiveness and migration of osteosarcoma U2OS cells in the absence of MMP‐2 gene." (PMID 38064181, 2023). "Overall, targeting the MMP‐2/CHK/MATK pathway could allow for more effective and better tolerated osteosarcoma treatment regimens compared to doxorubicin alone." (PMID 38064181, 2023). "Based on these findings, we propose that targeting intracellular/nuclear MMP‐2 may be a novel therapeutic strategy, as it impacts CHK/MATK expression and activity, a known tumor suppressor in osteosarcoma." (PMID 38064181, 2023). "Thus, we propose that the MMP‐2 gene is an additional target to consider, as it influences the gene and protein expression of the tumor suppressor CHK/MATK in osteosarcoma." (PMID 38064181, 2023). "Specifically, the treatment of ononin induces apoptosis, inhibiting cell proliferation, invasion, migration, and metastasis via blocking MMP2/9 expression and EGFR-Erk1/2 pathways, which was further validated using biomarkers in human osteosarcoma MG-63 xenograft mice." (PMID 36765716, 2023). "Mechanical stresses from the microenvironment have been reported to regulate the PI3K/Akt signaling pathway (the most activated downstream effectors in the oncogenic landscape), promoting the expression of MMP-2 and MMP-9, thus degrading ECM and enabling osteosarcoma cell invasion and metastasis." (PMID 37175397, 2023). "Silencing of TTYH1 inhibited the migration and invasion of the U2OS osteosarcoma cells and reduced the expression of epithelial-mesenchymal transition (EMT)-related factors such as SNAIL, Zinc E-Box Binding Homeobox 1 (ZEB1), matrix metalloproteinase 2 (MMP2), MMP9, and N-cadherin." (PMID 35455021, 2022). "Moreover, upregulated miR-124 significantly suppresses cell proliferation, invasion, and downregulates levels of MMP2 and MMP9 among osteosarcoma cells." (PMID 35184134, 2022). "Proliferation, invasion, and migration abilities of osteosarcoma cells and the level of protein expression of p-PI3K, p-Akt, MMP2, and MMP9 were significantly decreased with enhanced miR-652 expression (P < 0.01), while overexpression of HOXA9 reversed this situation." (PMID 35111226, 2022). "We also examined whether aprepitant could influence the gelatinase activities of MMP-2 and MMP-9 in the MG-63 osteosarcoma cell line." (PMID 36177059, 2022). "Furthermore, MMP-2 and MMP-9 have been found as potential therapeutic targets in different tumor types as well as osteosarcoma." (PMID 36177059, 2022). "BE503655 knockdown in osteosarcoma HOS cells could downregulate β-catenin as well as an array of Wnt cascade downstream targets, including c-Myc (a proto-oncogene), Cyclin D and MMP2." (PMID 34130697, 2021).
osteosarcoma (continued). "Consistent with their role in osteosarcoma, CCN proteins expression foster migration in chondrosarcoma by augmenting expression and enzymatic activity of MMP-13, MMP-2 or ICAM-1." (PMID 34228239, 2021). "Furthermore, upstream PI3K/Akt and ERK signaling pathways upregulate MMP2 and MMP9 expression, thus enabling osteosarcoma invasion and metastasis." (PMID 35145908, 2021). "In addition, western blotting revealed that the expression levels of MMP-2 and MMP-9 were decreased in osteosarcoma cells treated with both cordycepin and cisplatin for 48 h compared to those in the control group and those treated with either drug alone." (PMID 34953496, 2021). "Additionally, MMP-2, MMP-9, and MMP-13 overexpression has been revealed to be a promising indicator for osteosarcoma prognosis and pulmonary metastasis." (PMID 33228783, 2020). "Moreover, a dominant-negative soluble LPR5 reduces the expression of MMP-2 and MMP-14, consistent with a decrease in invasive properties of the human SaOS2 osteosarcoma cell line." (PMID 31370265, 2019). "In addition, MMP2 and MMP9 were subsequently upregulated through the c-jun pathway, and this finally promoted the migration and invasion ability of osteosarcoma cells." (PMID 31930127, 2019). "In addition, blocking the TGF-β cascade in tumor cells inhibits the expression and activation of MMP-2 and the ability of TGF-β to stimulate osteosarcoma cell migration and invasion." (PMID 29761075, 2018). "In this work, we showed that baicalein could not only reduce the protein expression but also decrease the enzymatic activity of MMP-2 and MMP-9, this results could partially explain the decline in osteosarcoma motility after treatment with baicalein." (PMID 29156780, 2017). "Interestingly, tectorigenin has been shown to inhibit cell migration through downregulation of MMPs, including MMP-2 and MMP-9, in osteosarcoma cells." (PMID 28264481, 2017). "A shift from MMP9 to predominant MMP2 activity is associated with poor response to chemotherapy suggesting that the ratio of MMP2/MMP9 activity might be a valuable and easily accessible marker to predict the response to chemotherapy in osteosarcoma." (PMID 26979530, 2016). "In this context, upregulation of MMP9 but not MMP2 has been shown to contribute to increased metastatic ability of osteosarcoma cells." (PMID 26979530, 2016). "Therefore, the down-regulation of MMP-2 and MMP-9 is related to the inhibition of osteosarcoma cell metastasis and is partly attributed to EMT reversal." (PMID 27144433, 2016). "To identify the action of miR-106b on RANKL, IL-8, MMP2 and TWIST we transfected GCTSCs and MG63 cells, a cell line of osteosarcoma known to express these cytokines, with agomiR-106b or antagomiR-106b and measured the mRNA and protein levels of RANKL by qRT-PCR, Western blot and ELISA." (PMID 26053181, 2015). "In addition to MAPK signals, FAK activation was suppressed by RESV in osteosarcoma cells, and FAK was reported to regulate MMP-2 activity in endothelial cells." (PMID 25605016, 2015). "Growth and development of osteosarcoma depends mainly on the activation of VEGF165, MMP2 and MMP9." (PMID 26109911, 2015). "MMP-2 and MMP-9 have been studied often in the context of osteosarcoma and pulmonary metastasis." (PMID 26202311, 2015). "Otherwise, we found that MMP-2 was highly expressed in tumor specimens rather than normal bone and was positively correlated with the distal metastasis status of Taiwanese osteosarcoma patients." (PMID 25605016, 2015). "We found that osteosarcoma U2OS and rhabdomyosarcoma RD normally secreted both MMP-2 and -9." (PMID 24190483, 2014). "Given that MMP-2 and MMP-9 are instrumental in tumor cell invasion, our results suggest the risedronate could reduce osteosarcoma cell invasion." (PMID 19624845, 2009). "Additionally, riluzole suppresses the activity of matrix metalloprotease-2 (MMP2) in most of the osteosarcoma cell lines (but not the PDX cells)." (PMID 40391158, 2025).
osteosarcoma (continued). "Hence, the present study aimed to investigate whether ononin inhibits osteosarcoma cell migration, invasion and proliferation through EGFR-Erk1/2 and MMP2/9 in MG-63, and U2OS and MG-63 xenograft mice." (PMID 36765716, 2023). "Additionally, EFEMP1 could promote the migration and invasion of osteosarcoma via MMP-2 with induction by AEG-1 via the NF-κB signaling pathway, and EFEMP1 was also reported to be an indicator of poor prognosis in osteosarcoma." (PMID 33587010, 2021). "CCN1 induces MMP-2, MMP-9, MMP-14 and TIMP-3, mediates prometastatic effects via the IGF-1/IGF1Rβ pathway, and is elevated in MG63 M7 and M10 sublines selected in vivo for a migratory phenotype; in addition, its inhibition decreases lung-metastatic potential of osteosarcoma cell lines in vivo." (PMID 34228239, 2021). "Therefore, it could be speculated that GSK-3β might promote the osteosarcoma metastasis by reducing the stability of PTEN and increasing the phosphorylation of FAK, and then accelerate the secretions of MMP-2 and MMP-9." (PMID 33969873, 2021). "Their hypothesis that doxycycline, a non-toxic antibiotic drug could, act either as an MMP-2 inhibitor or as an anti-neoplastic chemotherapeutic agent in osteosarcoma cells proved realistic." (PMID 32377334, 2020). "There were a small number of recent studies reporting prognostic biomarkers for osteosarcoma which were associated with lung metastases and survival such as PLA2G16, MMP-2, CXCR4 and MMP9, but none of them showed correlation with response to chemotherapy treatment." (PMID 28846700, 2017). "Generally, tumor cell invasion requires both cell migration and digestion of the basement membrane by MMPs, but zoledronate could not affect expressions and m-RNA levels of MMP-2 and -9 in 4 osteosarcoma cell lines." (PMID 26848867, 2016). "Moreover, nobiletin effectively suppressed SP-1 and CREB expressions, these findings are consistent with those in reports on leukemia cells, cholangiocarcinoma cells and osteosarcoma cells, implicating the importance of NF-κB and CREB in the regulation of MMP-2 and MMP-9 in U2OS and HOS." (PMID 27144433, 2016). "Among the more than 20 known members of the MMP family, especially MMP2 and MMP9 have been extensively studied in human cancers and have been shown to be closely related to the invasive potential and metastasis of different types of tumor cells including osteosarcoma." (PMID 26979530, 2016). "Furthermore, MMP9 activity and gene expression has been reported to correlate with the metastatic potential of rat osteosarcoma, while MMP2 could not be detected." (PMID 26979530, 2016). "In orthotopic osteosarcoma models lacking fusions, pharmacologic TrkA blockade dampened NGF-induced MMP-2 programs and reduced metastatic spread, consistent with the NGF/MMP axis observed in patient and cell-based datasets." (PMID 41567220, 2025). "Quantitative RT-PCR analysis of CTGF, MMP2, MMP-3, and miR-519d performed in osteosarcoma and normal samples, showed negative correlation between CTGF and miR-519d; positive correlation between CTGF and MMP-2, CTGF and MMP-3." (PMID 25003330, 2014). "However, IL-32 did not affect MMP-2 and MMP-9 expression in osteosarcoma cells whereas MMP-13 is involved in the IL-32-induced migration, suggesting that different types of proteases affects the migratory processes in a cell-type specific manner." (PMID 27589563, 2016). "As expected, a significant positive correlation was found between the secretion of u-PA and MMP-2/MMP-9 and a significant negative correlation between u-PA and TIMP-2 and between MMP-2/MMP-9 and TIMP-2 secretion by NM treatment of osteosarcoma and rhabdomyosarcoma cells." (PMID 23900236, 2013). "Therefore, given the known importance of MMP-2 and MMP-9 in tumor invasion, our findings suggest that the inhibitory effect of risedronate on osteosarcoma cell invasion is probably due to MMP inhibition rather than tumor cell death." (PMID 19624845, 2009).